ENSG00000252136
Gene: Small nucleolar RNA gene on chromosome 4 (105,105,987 to 105,106,094, forward strand). Ensembl gene ENSG00000252136.
Homologues: Paralogues in human: SNORA31B (81% identical), SNORA31 (66% identical).